TUBA1C (tubulin alpha 1c)
Diseases named in the same sentence as TUBA1C in open-access papers (continued):
Sharing a sentence is not in itself a finding about the gene and the disease.
sarcoma (2 papers, 2022). A usually aggressive malignant neoplasm of the soft tissue or bone. "Furthermore, DFI curves revealed that high expression of TUBA1C mRNA was correlated with an unfavourable prognosis of PAAD, LUAD, and sarcoma (SARC)." (PMID 36466547, 2022).
anaplastic astrocytoma (1 paper, 2022). "In anaplastic oligodendrocytoma (AO) and anaplastic astrocytoma (AA), TUBA1C was expressed at moderate levels." (PMID 35513790, 2022).
bladder tumors (1 paper, 2023). "Analysis of three independent public cohorts revealed that bladder tumor tissues have higher TUBA1C expression than adjacent normal tissues; univariate/multivariate Cox analysis revealed that high TUBA1C expression was associated with higher mortality rates and shorter survival times." (PMID 37528357, 2023). "To compare TUBA1C expression levels in bladder tumors and normal tissues, we first analyzed the RNA-Seq data on TUBA1C expression in the TCGA pancancer dataset." (PMID 37528357, 2023).
breast invasive carcinoma (1 paper, 2024). "Our analysis revealed that there was a significant positive association between TUBA1C and CD274 in several cancer types, including KIRC, kidney renal papillary cell carcinoma (KIRP), stomach adenocarcinoma (STAD), and breast invasive carcinoma (BRCA), among others." (PMID 39301023, 2024).
cataract (1 paper, 2025). Partial or complete opacity of the crystalline lens of one or both eyes that decreases visual acuity and eventually results in blindness. "Specifically, proteins including ACTN4, DCTN1, MYO18A, TUBA1C, TBCB, and TUBB4A, were downregulated in all cataract groups compared to controls." (PMID 41283652, 2025). "Across all cataract groups, actin and microtubule cytoskeletal proteins (ACTN4, DCTN1, TUBA1C, TBCB, TUBB4A) were significantly downregulated compared to controls, with the most marked suppression in ARC." (PMID 41283652, 2025).
cervical cancer (1 paper, 2022). A primary or metastatic malignant neoplasm involving the cervix. "In contrast, lower TUBA1C expression was also found in BRCA and cervical cancer (CESC)." (PMID 35513790, 2022).
ciliopathy (1 paper, 2021). A genetic disorder of the cellular cilia or the cilia anchoring structures, the basal bodies, or of ciliary function. "We identified 10 genes (STK38L, TUBB2A/B, CCNO, ARL13B, RFX2, RAB23, TUBA1C, CEP170B, and SPATA7) that are established or candidate ciliopathy genes." (PMID 34485842, 2021).
diffuse large B-cell lymphoma (1 paper, 2022). "TUBA1C mutations were found in 21 of the 32 cancer types, and diffuse large B-cell lymphoma had relatively higher mutation levels (>6%)." (PMID 36466547, 2022).
endometrial cancer (1 paper, 2022). Primary or metastatic malignant neoplasm involving the endometrium (mucous membrane that lines the endometrial cavity). "Further, we analyzed the enriched RNAs in apoptosis pathways, and the CPTAC database showed that their encoded proteins were upregulated in endometrial cancer tissues, including ITPR3, LMNB1, PARP1, PARP4, and TUBA1C." (PMID 36566215, 2022). "Then we analyzed the RNAs enriched in the apoptotic pathway through CPTAC database, and showed that the protein level of ITPR3, LMNB1, PARP1, PARP4, and TUBA1C were upregulated in endometrial cancer tissues." (PMID 36566215, 2022).
low grade glioma (1 paper, 2021). A grade I or grade II glioma arising from the central nervous system. "Our purpose was to study the expression of TUBA1C, its potential prognostic value, and its effects on the infiltration of immune cells of low-grade glioma (LGG)." (PMID 34721547, 2021).
lymph node metastasis (1 paper, 2021). "The univariate analysis indicated that an increased expression of TUBA1C was significantly correlated to the following parameters: age, stage, and lymph node metastasis." (PMID 33653340, 2021). "Multivariable analysis was performed by adjusting for the following factors: age, stage, lymph node metastasis, and TUBA1C expression." (PMID 33653340, 2021).
mesothelioma (1 paper, 2022). A usually malignant and aggressive neoplasm of the mesothelium which is often associated with exposure to asbestos. "Elevated expression of TUBA1C mRNA was correlated with unfavourable OS in KIRC, LAML, LGG, LUAD, mesothelioma (MESO), SKCM, and LIHC." (PMID 36466547, 2022).
multiple sclerosis (1 paper, 2023). A progressive autoimmune disorder affecting the central nervous system resulting in demyelination. "In general, it can be concluded that increase of the expression of LASP1 and S100A6 genes and decrease the expression of the TUBA1C gene in multiple sclerosis disrupts NFAT transcriptional activity." (PMID 36970516, 2023).
pancreatic adenocarcinoma (1 paper, 2024). "Importantly, the expression of TUBA1C significantly affected prognosis in various cancers, including ccRCC, LUAD, and pancreatic adenocarcinoma (PAAD)." (PMID 39301023, 2024).
panuveitis (1 paper, 2022). A disorder characterized by inflammation of the entire uvea which includes the iris, ciliary body, and choroid. "Anti-tubulin-alpha-1c detected significant direct correlation with the presence of posterior uveitis, panuveitis, and venous thrombosis as well as BVAS, C4, and protein/creatinine ratio." (PMID 35128589, 2022).
uveal melanoma (1 paper, 2022). A melanoma derived from melanocytes of the uveal tract. "We also found that TUBA1C was coexpressed with immune activation genes in all cancer types and with immunosuppressive genes in most cancers except uveal melanoma (UVM)." (PMID 35513790, 2022).
tumor (33 papers, 2017 to 2025). "It has been shown in multiple ccRCC cohorts that increased expression of TUBA1C is associated with advanced tumor grade and stage, poorer prognosis, and shorter times to recurrence." (PMID 39301023, 2024). "Patients with high TUBA1C expression exhibit a greater tumor mutation burden and increased genetic variation, which causes a worse prognosis." (PMID 39301023, 2024). "We identified TUBA1C as a key determinant of the immunosuppressive microenvironment of ccRCC and found that it was significantly associated with tumor progression, poor prognosis, and resistance to ICB therapy." (PMID 39301023, 2024). "We investigated functions of TUBA1C, its impact on tumor progression, and prognostic outcomes, and its association with immune cell infiltration across several cohorts." (PMID 39301023, 2024). "TUBA1C is an α-tubulin isoform involved in mitosis, and its dysregulation has been implicated in tumor progression." (PMID 37528357, 2023). "Survival analysis revealed that TUBA1C was a poor prognostic factor for 12 tumour types, and mutations, CNVs, and methylation affected the prognosis of some cancer types." (PMID 36466547, 2022). "TUBA1C, as a type of tubulin, is associated with tumor cell death and cell proliferation, and TUBA1C overexpression is predicted to have a poor prognosis (Li C.-W." (PMID 35910195, 2022). "Overall, TUBA1C was overexpressed in most cancers, and overexpression of TUBA1C was linked to poor prognosis and higher tumour grade in patients." (PMID 35513790, 2022). "A high expression of TUBA1C was significantly associated with the following parameters: different disease states (Tumor or Normal) (P < 0.05), pathological stage (P = 1.82e-04), overall survival (P = 3.8e−05), and disease-free survival (P = 0.047)." (PMID 33653340, 2021). "The results showed that TUBA1C was significantly overexpressed in tumor tissues and associated with poor prognosis indicated by Gene Expression Profiling Interactive Analysis (GEPIA) datasets." (PMID 32117719, 2020). "It has been proposed that TUBA1C is associated with tumor cell death and cell proliferation, and aberrant expression of ALDOB contributes to tumor metastasis, which is involved in the initiation and development of HCC." (PMID 30344796, 2018). "TUBA expression was also shown to be associated with tumor embolus, with 35.71% (10/28) in TUBA1C-high group and 10.34% (3/29) in the TUBA1C-low group (p=0.0295)." (PMID 29221200, 2017). "In this study, TUBA1C methylation was found to be associated with TUBA1C mRNA expression in a majority of tumours, and its hypermethylation resulted in better OS in PAAD, LGG, THCA, MESO, LIHC, and BRCA, which indicates the prognostic value of TUBA1C methylation." (PMID 36466547, 2022). "In addition, TUBA1C expression was associated with tumour mutation burden (TMB), microsatellite instability (MSI), the tumour microenvironment (TME) and the infiltration of immune cells." (PMID 35513790, 2022). "Our findings indicate that TUBA1C is associated with TIICs in tumor microenvironment." (PMID 33653340, 2021). "Therefore, we examined whether TUBA1C has mutations, and whether these mutations affect the prognosis of tumours." (PMID 36466547, 2022). "Some studies have found that TUBA1B and its homolog TUBA1C are involved in regulating immune cell infiltration within the tumor microenvironment." (PMID 40094001, 2025). "A comparative analysis revealed that TUBA1C and PD-L1 protein expression was significantly higher in tumor tissues than in their normal counterparts, both paired and unpaired." (PMID 39301023, 2024). "Studies have shown that when TUBA1C expression level is increased, the growth and progression of tumor cells are significantly affected." (PMID 39628476, 2024). "We injected LN299 cell lines transfected with either TUBA1C-NC or TUBA1C-Si-1 subcutaneously into nude mice and dynamically observed the body weight and tumor growth of the mice." (PMID 39355251, 2024).
tumor (continued). "This renders TUBA1C a promising therapeutic target whose suppression can potentially reverse the immunosuppressive tumor microenvironment, delay cancer progression, improve the response to ICB treatment, and prolong the survival of ccRCC patients." (PMID 39301023, 2024). "Our findings showed that patients with elevated TUBA1C expression displayed significantly higher tumor signature scores in several key areas, including hypoxia, exosomal secretion and assembly, extracellular vesicle biogenesis, and ferroptosis, among others." (PMID 39301023, 2024). "Elevated TUBA1C expression correlates with poor outcomes and with tumor-infiltrating immune cells (TIICs) in LUAD." (PMID 39355251, 2024). "Subsequently, TUBA1C expression levels in paired tumor tissue and adjacent tissue in the TCGA BLCA dataset were further evaluated and were found to be consistent with the previous results (P < 0.01)." (PMID 37528357, 2023). "A subcutaneous tumor model should be established and the role of TUBA1C in the body should be further elucidated." (PMID 36941595, 2023). "TUBA1C is involved in mitosis, and studies have reported that TUBA1C overexpression significantly affects the growth and progression of tumor cells." (PMID 37528357, 2023). "Current research suggests that the TUBA1C gene has the potential as a biomarker for tumor prognosis and immunotherapy outcomes." (PMID 37091145, 2023). "Recent studies have revealed that TUBA1C is involved in the cell cycle and cell proliferation in a variety of cancers and its upregulation can have dramatic effects on tumor growth and progression." (PMID 36941595, 2023). "The correlation analysis between TUBA1C expression and the clinical characteristics of these samples showed that high TUBA1C expression was correlated with survival time (P = 0.032), survival status (P = 0.043), and tumor size (P = 0.005)." (PMID 38032902, 2023). "We observed that in BRCA (p = 0.033), HNSC (p = 0.0038), KICH (p = 0.00022), KIRC (p = 0.00025), LUAD (p = 0.034), MESO (p = 0.02) and READ (p = 0.025), significant differences in TUBA1C expression existed between stage I and stage IV tumours." (PMID 35513790, 2022). "In LIHC (p = 0.0067), LUAD (p = 0.0027) and MESO (p = 0.022), the expression of TUBA1C was higher in stage III than in stage I tumours." (PMID 35513790, 2022). "Elevated expression of TUBA1C was correlated with poor outcome and with 13 tumour-infiltrating immune cells (TIICs) in LUAD." (PMID 35513790, 2022). "By performing immunohistochemical analysis, we found that the expression level of TUBA1C was higher in tumor tissues than in normal tissues." (PMID 33653340, 2021). "Previous studies have reported that when the expression of TUBA1C is up-regulated, it significantly affects the growth and progression of tumor cells." (PMID 33653340, 2021). "The results indicate that the expression of TUBA1C in tumor tissues was significantly higher than in normal tissues (P = 8.913e-21)." (PMID 33653340, 2021). "We found that TUBA1C was overexpressed in LGG tumor tissues compared to the normal tissues (p < 0.001)." (PMID 34721547, 2021). "We also determined the correlation between TUBA1C and tumor-infiltrating immune cells (TIICs) by using CIBERSORT and GEPIA databases." (PMID 33653340, 2021). "It showed that TUBA1C was significantly highly expressed in tumor tissues compared with normal tissue." (PMID 32117719, 2020). "The results showed that TUBA1C downregulation significantly suppressed the cell proliferation and cell cycle and markedly suppressed tumor growth and increased the apoptosis rate in vitro and in vivo." (PMID 32117719, 2020). "The expression of TUBA1C was significantly enhanced in tumor tissues compared to the adjacent normal tissues." (PMID 29221200, 2017). "The protein abundance of TUBA1C in the tumor tissues was also significantly higher than adjacent normal tissues, according to Western Blot results." (PMID 29221200, 2017).
tumor (continued). "In this article, we report that another oncogene, TUBA1C, as a component of tubulin, is significantly highly expressed in tumor tissues than the normal across datasets." (PMID 29221200, 2017). "Furthermore, PD-L1 was found to be positively correlated with TUBA1C expression in tumor tissues and co-localized on the cytomembrane of tumor cells." (PMID 39301023, 2024). "Understanding the interaction between TUBA1C and other immune-modulatory pathways could reveal new strategies for enhancing anti-tumor immunity." (PMID 39301023, 2024). "TUBA1C plays a role as a tumor promoter in most cancer types." (PMID 38891892, 2024). "Finally, using RT-qPCR, immunohistochemistry, and clinical cohort analysis, we confirmed that TUBA1C expression is upregulated at both the mRNA and protein levels in tumor tissue." (PMID 39301023, 2024). "Additionally, we did not perform in vivo animal experiments to investigate the function of TUBA1C in reshaping the tumor microenvironment, carcinogenesis, and resistance to ICB therapy as well as the underlying mechanisms." (PMID 39301023, 2024). "Although there were some discrepancies in the expression of TUBA1C between tumor stages and grades at the protein and mRNA levels, these differences can be attributed to the small sample sizes of advanced-stage and high-grade ccRCC patients in our clinical cohort." (PMID 39301023, 2024). "Moreover, TUBA1C plays a vital role in cell cycle signaling pathways and can significantly affect tumor growth and progression." (PMID 38048216, 2023). "In this study, it was shown that the tumor microenvironment and immune response may be modified by TUBA1C, which may inhibit or promote cancer progression." (PMID 37528357, 2023). "Finally, tumor xenograft models demonstrated that reduced levels of TUBA1C inhibited tumor growth in vivo." (PMID 36941595, 2023). "According to our findings, TUBA1C is involved in tumor immune infiltration in BLCA." (PMID 37528357, 2023). "This evidence suggests that TUBA1C is closely connected to tumor progression." (PMID 37528357, 2023). "As a prognostic marker, TUBA1C influences tumor progression by regulating the cell cycle." (PMID 37528357, 2023). "Since factors unrelated to the tumours may also contribute to death during follow-up, the relationship between TUBA1C expression and DSS in patients was subsequently analysed." (PMID 35513790, 2022). "Furthermore, TUBA1C exhibited a positive correlation with almost all immunosuppressive, chemotactic, and chemotactic receptor genes in LGG, LIHC, and THCA, suggesting that TUBA1C influences tumour development through immune-related genes in these cancers." (PMID 36466547, 2022). "In conclusion, TUBA1C functions as a tumour promoter in most cancer types." (PMID 35513790, 2022). "This suggests that TUBA1C may influence cancer progression and prognosis by affecting the tumour immune response." (PMID 35513790, 2022). "Furthermore, GSCA was used to examine the role of the TUBA family in tumour-related pathways to distinguish the functions of TUBA1C from those of other members of the TUBA family (TUBA1A and TUBA1B)." (PMID 36466547, 2022). "Therefore, future studies can further validate the role of TUBA1C in tumours through clinical trials or prospective studies." (PMID 36466547, 2022). "In conclusion, TUBA1C expression was correlated with tumour stage." (PMID 35513790, 2022). "The potential of TUBA1C as a new immunotherapeutic target for tumour therapy was revealed." (PMID 35513790, 2022). "TUBA1C is a member of the tubulin families and several studies demonstrated that its upregulation promotes oncogenesis and predicts poor prognosis in different tumour types." (PMID 35167614, 2022). "Moreover, we found that TUBA1C was correlated with the clinicopathological stage of cancers, which helps to determine the degree of malignancy of tumours." (PMID 35513790, 2022). "We next assessed the relationship between TUBA1C expression and tumour stage." (PMID 35513790, 2022).